CCL2 (C-C motif chemokine ligand 2)
Diseases named in the same sentence as CCL2 in open-access papers (continued):
Sharing a sentence is not in itself a finding about the gene and the disease.
breast cancer (continued). "In mouse models of breast cancer, the recruitment of CD11b-positive macrophages by CCL2 was reported to develop lung metastasis." (PMID 32726950, 2020). "In our previous study, we have shown that CCL2 controls breast cancer invasiveness via the ERK1/2 signaling." (PMID 32455851, 2020). "It was recently demonstrated that CCL2 derived from TAMs has led to elevated endocrine resistance in luminal-A breast cancer cells, through the activation of the PI3K/Akt/mTOR cascade." (PMID 32582148, 2020). "Specifically, leptin and lauric acid secreted by adipocytes and CCL2 secreted by breast cancer cells together enhance the chemotaxis of macrophages." (PMID 33224886, 2020). "Serum CCL2 levels in 135 breast cancer patients were measured and elevated and serum CCL2 levels were significantly correlated with advanced cancer stage and lymph node metastasis." (PMID 33297571, 2020). "In breast cancer models, Notch1 was induced by fibroblast-derived CCL2 to maintain a stem cell phenotype and had a possible oncogenic role." (PMID 32028262, 2020). "Here, we show that stromal CCL2 expression within developing mammary tumors enhanced end-stage tumor fibrosis." (PMID 32731354, 2020). "Specifically, we found that production of the chemokine CCL2 by breast cancer cells was significantly decreased after depletion of either CD44 or HA." (PMID 32455980, 2020). "In summary, our results identify a S100A14- NF-κB -CCL2/CXCL5 signaling axis in promoting breast cancer metastasis." (PMID 32483412, 2020). "Adipocytokines such as TNF-α, IL-1β, FGF-2, and CCL2 have also been found to be involved in the regulation of LOX expression in breast cancer." (PMID 33123472, 2020). "CCL2 induced Notch1 expression and the cancer stem cell features in breast cancer cells, constituting a “cancer–stroma–cancer” signaling circuit." (PMID 33244467, 2020). "Min Yao and her colleagues have found that the growth of primary tumors increased significantly with the cotransplantation of fibroblasts and the expression of CCL2 was high in a murine model of basal‐like breast cancer." (PMID 32253815, 2020). "CCL2 also stimulates the migration of mammary carcinoma cell lines, and mediates the recruitment of specific monocyte populations that support the establishment of metastatic disease." (PMID 33114046, 2020). "At the same time, we also report that Notch3 knockdown can inhibit the proliferation and the migration of 4T1 murine mammary carcinoma cells via the CCL2/CCR4 axis." (PMID 33244467, 2020). "In a mouse breast cancer lung metastasis animal model, CCL2 also promotes MDSC migration and triggers S100A8/A9 secretion." (PMID 30792719, 2019). "The results confirmed that TNF-α induces upregulation of CCL2 expression in both breast cancer cell lines and IL-6 expression in MDA-MB-231 cells." (PMID 31665136, 2019). "In summary, this study demonstrates that CCL2/CCR2 chemokine signaling in breast cancer cells is an important regulatory mechanism for cell growth and invasion." (PMID 31208996, 2019). "In previous studies, we demonstrated an important role for p42/44MAPK and SMAD3 in CCL2/CCR2 breast cancer cell motility." (PMID 31208996, 2019). "It would be of interest in the future to distinguish which pathways are mediated by paracrine versus autocrine CCL2/CCR2 signaling in breast cancer cells to regulate cell growth and invasion." (PMID 31208996, 2019). "ER− breast cancer is associated with elevated NF-κB activity, and shows increased expression of certain cytokines (IL-6, IL-8) and chemokines (CCL5, MCP-1 [CCL2])." (PMID 30736340, 2019). "Quantitative real-time PCR was used to investigate butein effect in CCL2 gene expression in both breast cancer cell lines." (PMID 31665136, 2019). "Mechanistically, lnc-BM induced STAT3-dependent expression of CCL2 to attract macrophages to cancer cells, thus enhancing breast cancer brain metastasis." (PMID 31448238, 2019).
breast cancer (continued). "While CCL2 is expressed in carcinoma cells, studies have indicated that CCL2 expression in the stroma is a more significant prognostic indicator in breast cancer." (PMID 31208996, 2019). "Using 3D cell culture and transwell invasion systems, we report that CCL2/CCR2 signaling regulates breast cancer cell growth and invasion in part by enhancing ALDH1A1 expression and suppressing HTRA2 expression." (PMID 31208996, 2019). "Using 3D Matrigel: Collagen cultures of SUM225 and DCIS.com breast cancer cells, this study characterized the mechanisms through which CCL2/CCR2 signaling regulated cell growth and invasion." (PMID 31208996, 2019). "In patients with breast cancer, a positive correlation of CCL2 with IL-1β and with macrophage marker CD68 in all breast cancer types was shown." (PMID 31921102, 2019). "While the importance of CCL2/CCR2 signaling in macrophages during cancer progression is well documented, we recently showed that CCL2-mediated breast cancer progression depends on CCR2 expression in carcinoma cells." (PMID 31208996, 2019). "Their results also suggested that the mammary epithelial cells around the adipose tissue secreted CCL2, leading to the recruitment of macrophages and formation of the crown-like structures (CLS) associated with malignant progression of breast cancer." (PMID 31500658, 2019). "To elucidate the mechanisms through which CCL2/CCR2 signaling regulated breast cancer cell growth and invasion, we first analyzed the effects of CCL2 treatment on DCIS.com and SUM225 breast cancer cell growth and invasion in 3D Matrigel: Collagen cultures." (PMID 31208996, 2019). "We found that ALDH1A1 and HTRA2 regulates CCR2-mediated breast cancer cell growth and cellular invasion in a CCL2/CCR2 context-dependent manner." (PMID 31208996, 2019). "To determine the molecular mechanisms through which CCL2/CCR2 signaling regulates breast cancer cell growth and invasion, we examined for expression of downstream factors." (PMID 31208996, 2019). "Here, CCL2 stimulation of CCR2 overexpressing cells enhanced growth and invasion more than CCR2 overexpression alone, further supporting an important role for paracrine CCL2/CCR2 signaling to breast cancer cells." (PMID 31208996, 2019). "Using 3D Matrigel: Collagen cultures of SUM225 and DCIS.com breast cancer cells, this study characterized the mechanisms of CCL2/CCR2 signaling in cell growth and invasion." (PMID 31208996, 2019). "In summary, CCL2/CCR2 chemokine signaling regulates breast cancer cell growth and invasion through increased ALDH1A1 expression and suppression of HTRA2." (PMID 31208996, 2019). "Mechanistically-wise, it was suggested that CCR2 regulates CCL2-induced breast cancer cell motility through MAPK- and Smad3-dependent mechanisms." (PMID 31350989, 2019). "Recent studies have shown that CCL2/CCR2 chemokine signaling in carcinoma cells enhances breast cancer growth and invasion." (PMID 31208996, 2019). "Although evidence in the literature show butein potential in protecting against and suppressing cancer, there are no studies to compare the effect of this compound on TNF-α-induced CCL2 release in Caucasian and African American breast cancer cell lines." (PMID 31665136, 2019). "Lnc-BM induces STAT3-dependent expression of CCL2 to attract macrophages, thus enhancing breast cancer brain metastasis." (PMID 31448238, 2019). "At the same time, in breast cancer cells, CCL2 can also induce the expression of NOTCH1 and the conduction of its downstream signals, thus inducing the activity of cancer stem cells (CSCs)." (PMID 31500658, 2019). "In breast cancer, CCL2/CCR2 axis coordinates cells survival and motility through Smad3 and MAPK-dependent mechanisms." (PMID 31501414, 2019). "Using a breast cancer model, the authors showed that chemotherapy-elicited EVs secreted by tumor cells induced pulmonary CCl2 expression, LyC6+ expansion and endothelial cell activation in lung, promoting the establishment of metastasis." (PMID 31597943, 2019).
breast cancer (continued). "Recruitment of macrophages to primary tumor sites is essential for tumor progression, and inhibition of CCL2 significantly reduces macrophage infiltration and mammary tumor growth in MMTV-PyMT mice." (PMID 30651598, 2019). "CCR2 mediates the migration of Ly6Chi monocytes from the bone marrow to CCL2-secreting tumor milieu in PyMT spontaneous breast carcinoma, KCKO pancreatic carcinoma, and MC38 colorectal carcinoma." (PMID 31474975, 2019). "In 4T1 and MMTV-PyMT breast carcinoma, paclitaxel treatment induces the secretion of tumor-derived extracellular vesicles (EVs), and these EVs upregulate pulmonary CCL2 expression to elicit classical monocyte expansion establishing a lung pre-metastatic niche." (PMID 31474975, 2019). "During anti-CCL2 treatment in 4T1, J110, and Met-1 mammary carcinoma, a large population of the classical monocytes is retained within the bloodstream, and their homing to the primary tumor or to the metastatic site is attenuated." (PMID 31474975, 2019). "The correlation between macrophage accumulation and Ccl2 expression has been demonstrated in breast carcinomas and Ccl2 neutralization was found to attenuate recruitment of inflammatory monocytes and reduce metastasis formation in tumor-bearing mice." (PMID 31406165, 2019). "In summary, our observations imply that hormonal regulation of CCL2 is essential to development and progression of HR-positive breast cancer." (PMID 29934505, 2018). "For example, in mice with mammary tumor developed by orthotopic injection of MDA-MB-231 human breast cancer cells, treatment with anti-CCL2 antibody reduces TAM accumulation, which results in the reduced micro-vessel density and tumor growth." (PMID 30483271, 2018). "In basal-like breast cancer, tumor cells secrete both CCL2 and IL-1β in a Notch-dependent manner, and the secreted cytokine/chemokines, in turn, recruit monocytes to the tumor site." (PMID 29686671, 2018). "Our observation, that CCL2 expression was not statistically related to HR status or Her-2 amplification, was intriguing since estradiol has been shown to play a key role in CCL2 modulation of ER+ breast cancer cells." (PMID 29934505, 2018). "According to our knowledge, there are no studies of the diagnostic criteria (sensitivity and specificity) of CCL2 and CCR2 serum or plasma levels in breast cancer patients." (PMID 30151375, 2018). "It is therefore likely that a population of breast cancer cells prompt stromal cells to secrete CCL2 for TAM accumulation in the tumors." (PMID 30483271, 2018). "Overexpression of DARC in human breast cancer cells has been reported to downregulate CCL-2 levels and subsequently inhibit the proliferation and metastasis of breast cancer cells in vivo and in vitro." (PMID 30140603, 2018). "Our current research reveals a previously unrecognized mechanism by which estrogen affects CCL2 regulation in ER+ breast cancer and identifies CCL2-CCR2 axis as a new feasible target for resistance to endocrinotherapy." (PMID 29934505, 2018). "One of the findings in our study was that of a statistically significantly increase of plasma CCL2 concentration in breast cancer patients compared to benign breast tumors." (PMID 30151375, 2018). "In a clinical trial on breast cancer patients, TGF-β expression was lower during the early stages of disease, but higher and associated with CCL2 levels during late stages." (PMID 30034291, 2018). "In a model of basal-like breast cancer, tumor cells secrete the CCL2 & IL-1β cytokines in a Notch dependent manner, which work to recruit monocytes." (PMID 30515368, 2018). "A positive correlation between IL-1B expression, OPG and CCL2 has been found in human breast cancer genome-wide mRNA expression array." (PMID 29760166, 2018).
breast cancer (continued). "The tumor modeling results are in agreement with another clinical study which reported that patients with breast cancer had higher CCL2 in serum than healthy controls and this elevated serum CCL2 is closely related to high malignancy and poor prognosis." (PMID 29934505, 2018). "In HR+ breast cancer, estrogen exposure exerts direct and indirect effects in promoting tumor growth and invasion via tumor-derived CCL2." (PMID 29934505, 2018). "During the stage of PMI, a series of immune-related genes expression were increased in the absence of inflammatory insult, such as interleukins (ILs), CC-chemokine ligand 2 (CCL2) and MMPs, which are also related to breast cancer development." (PMID 29423058, 2018). "First, to clarify the relationship between Twist and CCL2 expression in breast cancer, we detected their presence by IHC in 57 human breast tumor specimens." (PMID 29934505, 2018). "First, we examined CCL2 expression in the culture media of different breast cancer cell lines, including MCF-7, T47D, MDA-MB-231 and SK-BR-3." (PMID 29934505, 2018). "The data presented here reveals that breast cancer patients have a significantly higher level of plasma CCL2 and commonly used tumor marker CA 15-3 than control groups." (PMID 30151375, 2018). "Chemokines with well-known functions in mammary cancer include CCL2, CCL5, CCL19, CCL20, CCL21 and CCL22." (PMID 30572845, 2018). "The C-C motif chemokine ligand-2 (CCL2) promotes breast cancer metastasis through engagement with its receptor CCR2 on macrophages." (PMID 29720474, 2018). "Further, human breast cancer tissues can express high levels of CCL2 and CCL5 compared to the adjacent normal breast tissues." (PMID 30483271, 2018). "It is also reported that CCL2 is expressed in fibroblasts residing in breast cancer biopsies, and that human mesenchymal stem cells increase CCL2 secretion in response to conditioned medium from MDA-MB-231 breast cancer cells." (PMID 30483271, 2018). "Out of all the known chemokines, breast cancer cells express the CCL2 chemokine, the receptor of which is CCR2." (PMID 30151375, 2018). "The incidence of mammary tumours was higher in Mmtv-Ccl2 mice, with 14 of 18 mice (78%) developing a mammary gland tumour compared to 8 of 18 (44%) control mice developing a mammary gland tumour (p = 0.04)." (PMID 28077158, 2017). "There was also a significant decrease in mammary tumour-free survival in Mmtv-Ccl2 mice compared to control mice (p = 0.025); mean latency (mean ± SD) was 12.7 ± 1.0 weeks in Mmtv-Ccl2 mice, and 16.7 ± 1.4 weeks in control mice." (PMID 28077158, 2017). "We evaluated the association between the expression of IL-1β plus CXCL1 plus CCL2 plus S100A8 plus VEGF plus IL8 and outcomes in several cohorts of breast cancer patients." (PMID 29262555, 2017). "Experimental neutralisation of CCL2 with anti-CCL2 antibodies in mouse models of breast cancer metastasis, although limiting early metastatic processes, promoted metastasis following the cessation of therapy." (PMID 28210073, 2017). "Antibody or depletion of CCL2 blocked the recruitment of MDSCs and TAMs in tumor microenvironment and showed effects to inhibit pulmonary metastasis of murine mammary cancer." (PMID 28694739, 2017). "For instance, CCR2-expressing monocytes and macrophages can interact with tumor-derived CCL2 and aid the migration of macrophages to lung metastases in a breast cancer model." (PMID 28382036, 2017). "The TCGA data base was queried for relationship between CCL2 expression and relapse free survival of breast cancer patients and compared to subsets of breast cancer patients." (PMID 28143493, 2017). "Metastatic breast cancer is known to secrete CCL2 39, which can stimulate MDSC-like and trigger S100A8/A9 release." (PMID 28744322, 2017).
breast cancer (continued). "Clinical studies have indicated TAM levels are correlated with breast cancer prognosis, and experimental evidence showed that CCL2 levels are significantly associated with TAM numbers and TAM retention, implicating CCL2 in breast cancer progression." (PMID 28143606, 2017). "Recent studies have reported that CCL2 is overexpressed in a majority of solid cancer types, including breast cancer, prostate cancer, esophageal carcinoma, colon cancer, pancreatic cancer, ovarian cancer and NSCLC." (PMID 28424406, 2017). "We found high levels of RANTES/CCL5, MCP-1/CCL2, and G-CSF in the breast cancer individual cultures, supporting an important recruitment capacity of monocytes, but also of neutrophils." (PMID 28337194, 2017). "OPG, IL1B, and CCL2 mRNA in normal and breast cancer human tissue samples were determined by qPCR using a panel of commercially available cDNAs." (PMID 28143606, 2017). "For example, Fujimoto described a role for stromal CCL2 (MCP-1) in the recruitment of tumor promoting macrophages into early breast cancer lesions, a process which promotes tumor progression." (PMID 28143493, 2017). "While we find that CCL2 cannot be used as a prognostic factor of all breast cancer, but that it can be prognostic for distinct subtypes of breast cancer." (PMID 28143493, 2017). "Firstly, the association between CCL2/CCR2 axis and the MAPK pathways has been found in cervical cancer, breast cancer, colon carcinoma and melanoma cells." (PMID 28424406, 2017). "In still another study of 427 invasive ductal carcinoma breast cancer cases, the expression of CCL2 in the stroma of basal-like breast cancer correlated with significant reduction in recurrence-free survival." (PMID 28143493, 2017). "Overexpression of CCL2 also increased susceptibility to 7,12-Dimethylbenz(a)anthracene (DMBA)-induced mammary tumour development." (PMID 28077158, 2017). "Significantly, a similar interaction was important for the development of lung metastases in human breast cancer patients, with high CCL2 expression and macrophage infiltration indicative of a poor prognosis." (PMID 28382036, 2017). "CCL2 has been described as both supporting breast cancer growth and progression and inhibiting breast cancer progression." (PMID 28143493, 2017). "Studies in mice have implicated CCL2 of epithelial tumour cell origin, and macrophages expressing the CCL2 receptor, CCR2, as critical factors in metastasis of breast cancer to the bone and lungs." (PMID 28077158, 2017). "In an immunohistochemical analysis of CCL2 expression in 205 breast cancer patients, CCL2 was lower in those tumors with ER and progesterone receptor (PR) positivity and higher in basal like breast cancer." (PMID 28143493, 2017). "CCL2 blockade was reported to block the mobilization of monocytes from the bone marrow to the blood in a murine breast cancer model." (PMID 28769933, 2017). "After paclitaxel and doxorubicin treatment in PyMT-MMTV mammary carcinoma, increased recruitment of TAMs was found to be mediated by increased CSF-1, CCL2 and CXCL2." (PMID 28694739, 2017). "Fibroblasts in breast carcinoma models increase levels of pro-inflammatory chemokines, including CCL2 and CCL7, which enhance infiltration of myeloid immune cells (macrophages, neutrophils) promoting tumor angiogenesis." (PMID 28423685, 2017). "In primary prostate and mammary tumors, CCL2 overexpression correlates with recruitment of M2 polarized macrophages, a subpopulation of macrophages that facilitate tumor progression through secretion of growth and survival factors." (PMID 27283985, 2016). "It was shown that also macrophages are able to promote metastatic seeding of breast cancer cells through CCL2-triggered chemokine cascade or endothelial cells, which provide nutritional support to the growing tumor." (PMID 26759169, 2016). "Previous studies indicated that tumor-derived CCL2 can enhance progression and malignancy of breast cancer." (PMID 27564257, 2016).